GNRH2 (gonadotropin releasing hormone 2)
Description:
Stimulates the secretion of gonadotropins; it stimulates the secretion of both luteinizing and follicle-stimulating hormones.
Synonyms: GnRH-II; LH-RHII
Tractability: Antibody: its Gene Ontology location is reachable by antibodies, with high confidence; UniProt places it where antibodies can reach, with medium confidence; UniProt predicts a signal peptide or a membrane-spanning region.
Gene: Protein-coding gene on chromosome 20 (3,042,821 to 3,045,747, forward strand). Ensembl gene ENSG00000125787.
Subcellular location: Secreted
Pathways (Reactome):
Signal Transduction: G alpha (q) signalling events; Hormone ligand-binding receptors
Gene Ontology:
Molecular function: gonadotropin hormone-releasing hormone activity; gonadotropin-releasing hormone receptor binding; hormone activity
Biological process: signal transduction
Cellular component: extracellular region
Genetic constraint (gnomAD): Loss-of-function variants: 15 observed, 12.81 expected, observed/expected ratio (o/e) 1.17, 90% interval 0.78 to 1.75. The upper end of that interval is the gene's LOEUF score, 1.75, which puts it in group 6 of 6, group 1 being the genes least tolerant of losing a copy. Missense variants: 143 observed, 146.04 expected, observed/expected ratio (o/e) 0.98, 90% interval 0.85 to 1.12. Synonymous variants: 60 observed, 63.63 expected, observed/expected ratio (o/e) 0.94, 90% interval 0.76 to 1.17.
Homologues: Orthologues: macaque GNRH2 (88% identical), chimpanzee GNRH2P (65% identical), pig GNRH2 (65% identical), tropical clawed frog gnrh2 (27% identical), zebrafish gnrh2 (20% identical), zebrafish gnrh3 (20% identical). Paralogues in human: GNRH1 (16% identical).
Diseases named in the same sentence as GNRH2 in open-access papers:
GNRH2 is named in the same sentence as 32 diseases in open-access papers, as found by Europe PMC text mining. Sharing a sentence is not in itself a finding about the gene and the disease. The quoted sentences say what the papers report.
ovarian carcinoma (9 papers, 2009 to 2023). A malignant neoplasm originating from the surface ovarian epithelium. "Subsequent studies have been conducted to determine the mechanism underlying anti-proliferative effects of GnRH2 on ovarian cancer cells." (PMID 38260130, 2023). "Due to its potent anti-proliferative effects, GnRH2 has garnered attention as a possible therapeutic for ovarian cancer treatment." (PMID 38260130, 2023). "Many researchers have investigated pro-apoptotic activities of GnRH2 analogues on ovarian cancer cells." (PMID 38260130, 2023). "Recent data also demonstrated that co-treatment of ovarian cancer cells with a glycolysis inhibitor and a GnRH2 antagonist reduced cell viability and increased apoptosis to a greater extent than each treatment individually." (PMID 38260130, 2023). "Additional research demonstrated that GnRH2 treatment inhibited mitogenic effects of EGF in ovarian cancer cells." (PMID 38260130, 2023). "GnRH2 antagonists induced apoptosis by activating caspase-3 and effectively inhibited growth of human ovarian cancer xenotransplants in nude mice." (PMID 38260130, 2023). "GnRH2 also increased metalloproteinase production, key regulators of tumor invasion, in ovarian cancer cells." (PMID 29312140, 2017). "GnRH2 expression in ovarian cancer cells appears to be mediated in part by gonadotropins." (PMID 38260130, 2023). "However, GnRH2 was the most potent competitor, indicating the presence of a functional 5-TM GnRHR2 in human ovarian cancer cells." (PMID 38260130, 2023). "GnRH2 expression is also regulated by EGF in ovarian cancer cells." (PMID 38260130, 2023). "The role of GnRH2 in ovarian cancer metastases has also been explored." (PMID 38260130, 2023). "Thus, in SKOV-3 cells, GnRH2 inhibits ovarian cancer invasion by regulating the balance of MMP2/TIMP2, and disrupting AKT-mediated proteolysis and invasion." (PMID 38260130, 2023). "In addition, treatment with a GnRH2 agonist reduced cell proliferation and inhibited the mitogenic effects of epidermal growth factor in human endometrial and ovarian cancer cells." (PMID 29312140, 2017). "Treating SKOV-3 cells with either GnRH1 or GnRH2 led to reduced MMP-2 expression and increased secretion of tissue inhibitor of MMP-2 (TIMP2), both important mediators of ovarian carcinoma metastasis." (PMID 38260130, 2023). "Furthermore, GnRH1 and GnRH2 disrupted activation of the phosphatidylinositol-3-kinase (PI3K)/AKT pathway, which promotes proteolysis and invasion in ovarian cancer cells." (PMID 38260130, 2023). "In SK-OV-3 ovarian cancer cells (expressing GnRHR2 but not GnRHR1), GnRH2 exhibited powerful anti-proliferative effects, unlike triptorelin, suggesting that GnRHR2 is mediating these effects." (PMID 38260130, 2023).
breast carcinoma (8 papers, 2010 to 2024). "GnRH2 antagonists stimulated loss of mitochondrial membrane potential and apoptosis in breast cancer cells via p38 MAPK and c-Jun N-terminal kinase (JNK) pathways, culminating in activation of the pro-apoptotic protein, BAX." (PMID 38260130, 2023). "Others identified direct anti-proliferative effects of GnRH2 on breast cancer cells." (PMID 38260130, 2023). "Moreover, GnRH2 expression in breast cancer samples correlated with indices of a poorer prognosis." (PMID 38260130, 2023). "Furthermore, a GnRH2 agonist reversed 4OH-tamoxifen insensitivity of breast cancer cells." (PMID 38260130, 2023).
endometrial cancer (8 papers, 2009 to 2024). Primary or metastatic malignant neoplasm involving the endometrium (mucous membrane that lines the endometrial cavity). "Triptorelin, cetrorelix (pan GnRHR antagonist), and GnRH2 exerted anti-proliferative effects on endometrial cancer cells (Ishikawa, HEC-1A, and HEC-1B) that produce GnRHR1 and GnRHR2 transcripts." (PMID 38260130, 2023). "GnRH2 induced apoptosis and suppressed cell proliferation in endometrial carcinoma cell lines, with a greater effect observed in cells with PTEN knockdown." (PMID 38260130, 2023). "Co-expression of GnRH2 and GnRHR2 suggest an autocrine/paracrine role in endometrial cancers." (PMID 38260130, 2023). "Notably, GnRH2 analogues have a more potent inhibitory effect than GnRH1 on proliferation of endometrial cancer cells." (PMID 38260130, 2023). "GnRH2 also has anti-proliferative effects in endometrial cancer cells." (PMID 38260130, 2023). "Several independent groups determined that GnRH2 analogues reduced endometrial cancer cell growth." (PMID 38260130, 2023). "Interestingly, radiolabeled GnRH2 binds a 43-kDA protein in human endometrial cancer cells." (PMID 38260130, 2023).
prostate carcinoma (5 papers, 2014 to 2024). A carcinoma that arises from epithelial cells of the prostate gland. "A recent study found an association between prostate cancer progression and a GnRH2 gene polymorphism in Japanese men, although a separate study did not observe this link in Caucasian men." (PMID 38260130, 2023). "Furthermore, GnRH2 gene polymorphisms were associated with elevated testosterone levels and an increased prostate cancer risk." (PMID 38260130, 2023). "GnRH2 treatment reduced proliferation of all tested prostate cancer cell lines; these results were ascribed to GnRHR1 and activation of cAMP." (PMID 38260130, 2023). "Photoaffinity labeling suggested that GnRH2 binds with high affinity to a protein in prostate cancer cells, implicating GnRHR2." (PMID 38260130, 2023). "Consistent with this, GnRH2 expression is elevated in prostate cancer cells (e.g., LNCaP cells) that produce androgen receptors (ARs) compared to those lacking ARs (e.g., PC3 cells) and AR inhibition blocked androgen-mediated increases in GnRH2 expression in LNCaP cells." (PMID 38260130, 2023). "Therefore, GnRH2 and GnRHR2 may be involved in autocrine/paracrine regulation of prostate cancer progression." (PMID 38260130, 2023).
Infertility (2 papers, 2022 to 2023). "Differences in DNAm in the GNRH2 gene during breastfeeding are consistent with the adaptive suppression of ovarian function during breastfeeding and may be a target for research on the link between obesity, metabolism and infertility." (PMID 35169479, 2022).
bone cancer (1 paper, 2023). A primary or metastatic malignant neoplasm affecting the bone or articular cartilage. "Further study is especially important given the recent discovery that a single nucleotide polymorphism in the GnRH2 gene is associated with both GnRH2 expression in the testis as well as bone cancer risk." (PMID 38260130, 2023).
cervical cancer (1 paper, 2023). A primary or metastatic malignant neoplasm involving the cervix. "There is a critical need to better understand the potential function of GnRH2 and GnRHR2 in these cells since cervical cancer is the second most common cancer in women." (PMID 38260130, 2023).
Gastrointestinal dysmotility (1 paper, 2017). Abnormal intestinal contractions, such as spasms and intestinal paralysis, related to the loss of the ability of the gut to coordinate muscular activity because of endogenous or exogenous causes. "Reduced numbers of enteric neurons and IgM antibodies against GnRH and progonadoliberin-2 (precursor of GnRH2) have been observed after such treatment, with the clinical picture of gastrointestinal dysmotility." (PMID 28638366, 2017).
leiomyoma (1 paper, 2023). A well-circumscribed benign smooth muscle neoplasm characterized by the presence of spindle cells with cigar-shaped nuclei, interlacing fascicles, and a whorled pattern. "However, transcripts for both GnRH2 and GnRHR2, as well as protein for GnRH2, were detected in normal myometrial tissue and leiomyomas of women, suggesting a direct effect of GnRH analogues on fibroid growth." (PMID 38260130, 2023).
osteosarcoma (1 paper, 2020). A usually aggressive malignant bone-forming mesenchymal neoplasm, predominantly affecting adolescents and young adults. "The study aimed to evaluate the effects of common variants in MDM2 and GNRH2 genes on the risk and survival of osteosarcoma in Han populations from Northwest China." (PMID 32994424, 2020). "Accumulating evidence has shown that both MDM2 and GNRH2 might be related to Osteosarcoma (OS) susceptibility." (PMID 32994424, 2020).
ovarian tumor (1 paper, 2023). "Notably, in post-menopausal women with ovarian tumors, there was a positive correlation between serum LH and FSH concentrations and GnRH2 expression in ovarian tumor samples, suggesting a stimulatory role of the gonadotropins on GnRH2 expression in vivo." (PMID 38260130, 2023).
prostate tumors (1 paper, 2023). "Androgens enhanced GnRH2 expression in prostate tumors by binding a putative androgen response element on the 5’ flanking region of the human GnRH2 gene." (PMID 38260130, 2023).
testicular cancer (1 paper, 2023). A primary or metastatic malignant neoplasm that affects the testis. "Although GnRH2 and GnRHR2 have been investigated in the regulation of many different reproductive cancers, there is a gap in our knowledge regarding the potential influence of GnRH2 and GnRHR2 as a therapeutic to treat testicular cancer." (PMID 38260130, 2023).
cancer (12 papers, 2010 to 2023). A tumor composed of atypical neoplastic, often pleomorphic cells that invade other tissues. "In addition, further exploration of the connection between methylations/mutations in the GnRH2 gene with the onset of cancer is essential." (PMID 38260130, 2023). "Growing evidence indicates that treatment of cancer cells with GnRH2 analogs inhibits their proliferation." (PMID 29312140, 2017). "More recent work utilizing immortalized human cancer cell lines has further explored GnRH2-induced signaling." (PMID 29312140, 2017). "In addition, GnRH2 and its receptor have been detected in a wide number of reproductive cancer cells in humans." (PMID 38260130, 2023). "However, GnRH2 and/or GnRHR2 are also expressed in other reproductive cancer cells (cervical, placenta), warranting further study." (PMID 38260130, 2023). "Notably, GnRH2 and its analogues mediate potent anti-proliferative and pro-apoptotic activities in many different reproductive cancer cells suggesting an overall inhibitory role." (PMID 38260130, 2023). "Recently, GnRH2 and GnRHR2 have been detected in reproductive cancer cells." (PMID 38260130, 2023). "Like GnRH1, GnRH2 analogues inhibit cancer cell proliferation; however, GnRH2 is often more potent." (PMID 38260130, 2023). "GnRH2 and its receptor may also influence the progression of reproductive cancers, given that both are expressed in cancer cells and tumors derived from reproductive tissues." (PMID 29312140, 2017). "Furthermore, both the GnRH2 and GnRHR2 genes are expressed in human reproductive tumors and represent emerging targets for cancer treatment." (PMID 29312140, 2017). "In some human cancer cell models GnRH II(GNRH2, O43555) is more potent than GnRH I (GNRH1, P01148), implying mediation by GnRH2 receptors, but GnRH2 receptors are not expressed by humans because the human GNRHR2 gene contains a frame shift and internal stop codon [1377]." (PMID 29055040, 2017). "Thus, GnRH2 and possibly its receptor, regulate cancer cell proliferation/survival and represent emerging targets for the development of new cancer therapies." (PMID 29312140, 2017). "Furthermore, both GnRH2 and GnRHR2 are expressed in human reproductive tumors and are emerging targets for cancer treatment." (PMID 29312140, 2017). "In addition to anti-proliferative actions, GnRH2 analogs may also exert pro-apoptotic effects on cancer cells." (PMID 29312140, 2017). "Thus, GnRH2 and GnRHR2 may be novel, unexploited cancer targets." (PMID 38260130, 2023). "Furthermore, the contribution of GNRH2, PRLH, GPR156, GRIK5, LHB, and CRHR2 to the neuroactive ligand-receptor interaction pathway are specified in ATLL in consistent with some other cancers." (PMID 34446027, 2021). "In human cancer cells with reduced GnRHR1 levels, GnRH2 (not GnRH1) retained the ability to inhibit cell proliferation." (PMID 29312140, 2017). "Moreover, new data suggests that differential methylation of GnRH2 may affect cancer progression in non-reproductive organs." (PMID 38260130, 2023).
tumor (6 papers, 2010 to 2024). "For example, glioblastoma-derived microvesicles increased proliferation of tumor cells in vitro; the same microvesicles were also found to carry GnRH2, GnRH1, GnRHR2, and GnRHR1 mRNA." (PMID 29312140, 2017). "Indeed, GnRH2 analogues conjugated to cytotoxic drugs (e.g., daunorubicin) have shown promising anti-tumor effects in vitro." (PMID 38260130, 2023). "Importantly, the anti-tumor effects of GnRH2 are often more robust than GnRH1, enhancing therapeutic potential." (PMID 38260130, 2023). "Thus, anti-androgen therapy reduces GnRH2 expression in tumor biopsies." (PMID 38260130, 2023).
GNRH2 also shares sentences with these, for which no sentence is quoted: endometriosis (2 papers); hypothyroidism (2); autonomic dysfunction (1); breast tumors (1); diabetes mellitus (1); embryonal carcinoma (1); endometrial tumors (1); glioblastoma (1); gynecologic cancer (1); irritable bowel syndrome (1); mixed germ cell tumor (1); neuropathy (1); Obesity (1); primary Sjögren’s syndrome (1); reproductive tumors (1); seminoma (1); triple-negative breast carcinoma (1).